SOX17 (SRY-box transcription factor 17)
Diseases named in the same sentence as SOX17 in open-access papers (continued):
Sharing a sentence is not in itself a finding about the gene and the disease.
breast carcinoma (continued). "Thus SOX17 can be a useful biomarker for breast cancer patients." (PMID 31874629, 2019). "In breast cancer, ASMTL-AS1 expression is significantly downregulated, which triggers the Wnt/β-catenin signaling pathway via the miR-1228-3p/SOX17 axis." (PMID 39028420, 2024). "It was discovered that the DNA hypermethylation of tumor suppressor genes (SOX17, CST6, and BRMS1) was a characteristic of CTCs in patients with breast cancer." (PMID 35982906, 2022). "We compared the methylation status of three genes, SOX17, CST6 and BRMS1 in primary tumours, corresponding CTCs and ctDNA in 153 breast cancer patients and healthy individuals, by using real time methylation specific PCR." (PMID 29069768, 2017). "We found that the expression levels of SOX7, SOX17 and SOX18 were reduced significantly in breast cancer tissues compared to normal controls." (PMID 27188720, 2016). "Firstly, using gene expression files, we found that the expression of SOX7, SOX17 and SOX18 was significantly reduced, whereas SOX4 was markedly increased in breast cancer tissues compared to normal tissues." (PMID 27188720, 2016). "For instance, transcription factor SOX17 (SOX17), slit guidance ligand 3 (SLIT3), and cysteine dioxygenase type 1 (CDO1) that are frequently suppressed by hypermethylation in breast cancer, turned hypomethylated after resveratrol treatment." (PMID 27355345, 2016). "We compared the expression levels of SOX7 and other co-expressed genes in the Wnt/β-catenin pathway and found that the expression of SOX7, SOX17 and SOX18 was all reduced significantly in the breast cancer tissues compared to normal controls." (PMID 27188720, 2016). "In endoderm formation, β-catenin interacts with Sox17 independently of TCF-4 to activate endoderm genes and in breast cancer, β-catenin and Sox2 interact independently of TCF-4 to activate Cyclin D1." (PMID 20811503, 2010). "Examples of a PRC2 target, SOX17, and of a DNase Hypersensitive region containing a CTCF-binding site upstream of histone HIST1H4D illustrate the progressive DNAm increases from normal to normal adjacent tissue to breast cancer." (PMID 26823093, 2016). "SOX17 has been reported as an important transcription factor involved in different physiological processes, and may be a valuable biomarker for various cancers such as ESCC, colorectal cancer, and breast cancer." (PMID 35614065, 2022).
seminoma (27 papers, 2013 to 2026). A radiosensitive malignant germ cell tumor found in the testis (especially undescended), and extragonadal sites (anterior mediastinum and pineal gland). "So, PRAME expression correlates to SOX17 expression and can be associated with a PGCs / seminoma cell fate." (PMID 28244655, 2017). "In fact, SOX2 and SOX17 serve as markers for diagnostic discrimination between seminomas and ECs." (PMID 27283990, 2016). "Additionally, global 5mC levels remained unaffected and expression of seminoma-associated genes SOX17, PRAME, TFAP2C, PRDM1 and cKIT was maintained." (PMID 27283990, 2016). "SOX2 expression is predominantly restricted to embryonic carcinoma, followed by mixed germ cell tumors and one case of yolk sac tumor, whereas SOX17 is mainly in seminoma with several cases of mixed germ cell tumors and one case of embryonic carcinoma." (PMID 39996497, 2025). "Key transcription factors (TFs) such as TFAP2C, SOX17, OCT4/POU5F1 and NANOG are highly expressed in PGCs, and consequently are excellent diagnostic markers for seminoma and GCNIS14,18,19." (PMID 38123589, 2023). "Gene expression of pluripotency markers as well as markers of proliferation and cell cycle activity were upregulated in Tcam-2 cells in cocultures with T cells, whereas gene expression of SOX17, a marker for seminomas, was unaltered." (PMID 35269507, 2022). "We suggested previously that during in vivo differentiation of TCam‐2 cells into a non‐seminoma including aYST‐like structures, SOX17 switches function from pluripotency‐promoting to differentiation‐inducing as a result of FOXA2 up‐regulation." (PMID 33448076, 2021). "In our study, we highlight FOXA2 as a key driver of p/aYST formation acting in concert with SOX17, which already has been found up‐regulated in p/aYSTs versus seminomas." (PMID 33448076, 2021). "We propose that in ECs, seminomas and PGCs, SOX17 is able to switch from a pluripotency‐promoting to a differentiation‐inducing factor upon microenvironment‐triggered FOXA2 induction, driving differentiation into YST lineage." (PMID 33448076, 2021). "We stratified the TCGA testicular cancer cohort into seminomas (SOX17+) and non-seminomas (SOX2+ (EC), AFP+ (yolk-sac tumor), beta-hCG+ (choriocarcinomas)." (PMID 32272809, 2020). "Most importantly, the majority of TCam-2-ΔSOX2 cells maintains a seminoma-like cell fate for at least 6 weeks in vivo, indicated by a typical seminoma-like morphology and expression of seminoma markers SOX17, PRAME, TFAP2C and PRDM1 (nuclear)." (PMID 27283990, 2016). "ECs and seminomas express the pluripotency markers NANOG and OCT3/4, but SOX2 is detected in ECs only and is thought to be compensated by SOX17 in seminomas." (PMID 27283990, 2016). "In human seminomas/TCam-2 cells, SOX17 and OCT3/4 are expressed, but endodermal differentiation programs are suppressed." (PMID 27283990, 2016). "During this reprogramming, BMP signaling is inhibited, leading to induction of NODAL signaling, upregulation of pluripotency factors and downregulation of seminoma markers, like SOX17." (PMID 27283990, 2016). "In TCam-2-ΔSOX2 clones, expression of seminoma markers SOX17, PRAME, TFAP2C, LIN28 and PRDM1 was slightly downregulated or remained unchanged compared to the TCam-2 in vitro cells." (PMID 27283990, 2016). "PRDM1, the transcription factor TFAP2C and SOX17 render the PGCs and seminomas in a state of dormant pluripotency, meaning that they express pluripotency markers, but are not able to induce differentiation into somatic tissues." (PMID 26226633, 2015). "In these somatic microenvironments, TCam-2 cells upregulate EC-markers SOX2, CD30, DNMT3B/L and downregulate seminoma markers SOX17, cKIT and PRDM1." (PMID 26226633, 2015). "Among them, GDF3, NODAL, LEFTY1 /2, GAL, DPPA3, SOX2, DNMT3B /L, DPPA5, BCAT1, FGF2, PRDM14, ZIC3 and FZD7, while seminoma markers SOX17, cKIT and PRAME were downregulated." (PMID 26226633, 2015).
seminoma (continued). "In fact, SOX17 has been proposed as a useful marker to distinguish seminoma from EC cells and is down-regulated in differentiated seminoma cell line TCam-2." (PMID 23457636, 2013). "Specifically, high expression of STELLA and SOX2 is observed in EC cells compared with seminoma and vice versa for SOX17." (PMID 23457636, 2013). "We found TFAP2C and SOX17 also highly expressed within the areas of seminoma in the spatial data." (PMID 38123589, 2023). "In contrast, the typical seminoma marker SOX17 was unaltered in cocultured Tcam-2 cells." (PMID 35269507, 2022). "In the SOX17+/SOX2‐/CD24‐ seminoma cell line TCam‐2, only negligible binding intensities of SOX17 to CD24 could be detected (peak intensities < 15)." (PMID 34293822, 2022). "Given the high similarity between SOX factors and that SOX2 and SOX17 share similar functions in regulating pluripotency in ECs and seminomas, respectively, it seems reasonable that both factors are able to switch their functions in dependency of the interacting partner." (PMID 33448076, 2021). "Furthermore, SOX17 is highly expressed in seminomas, where it is thought to support pluripotency by functionally replacing SOX2." (PMID 31130628, 2019). "During further differentiation, FOXA2, SOX17, pluripotency and seminoma markers are downregulated." (PMID 31130628, 2019). "Thus, SOX17 / PRAME is critically important for maintenance of an undifferentiated dormant pluripotent seminoma fate." (PMID 28244655, 2017). "Additionally, many pluripotency and EC associated genes, like SOX2, ZIC3, ZFP42, LIN28, SALL4 and PRDM14 were upregulated without correlating to changes in their 5mC status, while seminoma markers SOX17, cKIT, PRDM1 and PRAME were downregulated." (PMID 27283990, 2016). "Distinction between seminoma and embryonal carcinoma could therefore be made by the expression of SOX17/CD38 and SOX2/CD30, respectively." (PMID 25543152, 2015). "Thus, cultivation of EC cells / cell lines in ‘4i’ medium, while overexpressing SOX17 simultaneously, might trigger reprogramming of ECs to a seminoma." (PMID 28244655, 2017). "However, with downregulation of PGC- (PRDM1, TFAP2C, cKIT) and pluripotency (NANOG, OCT3/4, LIN28) marker genes, persisting SOX17 expression together with activation of the Hippo pathway resulted in differentiation into a mixed non-seminoma with predominant choriocarcinoma-like components." (PMID 26226633, 2015). "Furthermore, additional EC and pluripotency genes were upregulated (SOX2, LEFTY1 /2, DNMT3L, SALL4, DPPA5, BCAT1, FZD7, LIN28, ZIC3), while seminoma-associated genes where downregulated (SOX17, TFAP2C, cKIT, PRAME), without changing 5mC-levels." (PMID 26226633, 2015). "Indeed, as expected no SOX2 is expressed, in line with the seminoma type of cells, linked to expression of SOX17 instead of SOX2." (PMID 24404135, 2014). "As expected, seminoma and PGCs shared specific expression of genes (C2) such as TFAP2C, POU5F1, NANOG and SOX17." (PMID 38123589, 2023). "PRAME is downstream of SOX17 and LIN28 for regulating pluripotency and controlling germ cell differentiation in seminoma cells." (PMID 38132219, 2023). "We found that seminoma and PGCs display strong similarities in their transcriptomes, especially by sharing the expression of key TFs such as TFAP2C, POU5F1, NANOG and SOX17." (PMID 38123589, 2023). "Two precursor lesions for testicular germ cell tumors type II, germ cell neoplasia in situ (GCNIS) and microinvasive germ cell tumor (MGCT), and seminoma (SE) also express an OSKM panel, with SOX17 as substitute for SOX2." (PMID 36835562, 2023). "TCam-2 cells express typical primordial germ cell and GCNIS marker genes (SOX17, PRAME, cKIT, TFAP2C, PRDM1/BLIMP1) and show a typical GCNIS/seminoma morphology (big roundish cells with a big nucleus and clear cytoplasm)." (PMID 31130628, 2019). "Analyses of these cells revealed downregulation of the pluripotency and seminoma markers OCT3/4, SOX17, PRDM1 and TFAP2C." (PMID 27283990, 2016).
seminoma (continued). "Further, it is known that SOX17 antagonizes WNT signaling activity, which has been suggested to be low in seminomas and high in ECs." (PMID 26226633, 2015). "Transcriptome analysis of hPGCLC and comparison with authentic in vivo wk7-wk9 hPGCs, and a seminoma cell line showed that they shared expression of key PGC genes, among which were SOX17 and a cell surface marker CD38." (PMID 26028529, 2015). "Further, it is known that SOX17 antagonizes WNT signaling, which has been suggested to demarcate seminomas from ECs." (PMID 26226633, 2015). "The marker genes SOX17 and SOX2 are differentially expressed between seminoma and ECs and serve as marker for transition." (PMID 24386123, 2013). "In contrast, mRNA levels of SOX17, which is a marker of seminoma cells, were similar in Tcam-2 cells regardless of the presence of T cells." (PMID 35269507, 2022). "We also checked whether SOX17, which in part shows redundancy to SOX2 in regulating pluripotency in seminomas, binds to CD24 as well." (PMID 34293822, 2022). "Seminomas typically express SOX17 in their nuclei and are negative for SOX2, known to be not expressed in human PGCs, while EC cells express SOX2 and are negative for SOX17." (PMID 34205983, 2021). "The increased Fgf5 mRNA expression in human melanoma cells in vitro increased clonogenicity and invasion without increasing growth, while the Sox17 in seminoma and primordial germ cells is not a marker of endodermal initiation but supports latent pluripotency." (PMID 33217978, 2020). "Additionally, strong and comparable expression of the seminoma and pluripotency markers OCT3/4, NANOG, LIN28, SOX17, PRAME, PRDM1/BLIMP1 and TFAP2C was found in TCam-2, TCam-2-ΔSOX2 and TCam-2-ΔSOX2/FOXA2 cells." (PMID 31130628, 2019). "In seminoma-like TCam-2-ΔSOX2 cells SOX17 expression is maintained and presumably partners with OCT3/4 to bind the canonical motif, triggering expression of PGC-, GCNIS- and seminoma-related genes, allowing keeping up the seminoma-like cell fate." (PMID 27283990, 2016). "Thus, in undifferentiated seminomas it is highly likely that SOX17 is redundant to SOX2 and promotes expression of pluripotency factors in combinaton with OCT3/4, thereby maintaining a GCNIS/seminoma-like cell fate." (PMID 27283990, 2016). "Both, seminomas and EC express the pluripotency markers OCT3/4 and NANOG, but expression of the pluripotency factor SOX2 is restricted to ECs, while seminomas express SOX17 instead." (PMID 26226633, 2015). "Thus, seminomas show expression of CD38 and SOX17 whereas embryonal carcinomas show expression of SOX2 and CD30." (PMID 26028529, 2015). "In contrast, expression of proposed YST key factors could clearly be associated with YST tissues and YST‐containing mixed GCTs, but not with ECs or seminomas (except SOX17 and GATA4)." (PMID 33448076, 2021). "Expression of typical seminoma markers (PRDM1/BLIMP1, SOX17, PRAME, TFAP2C) was also detectable in TCam-2-ΔSOX2/FOXA2 tumor tissues, in contrast to EC reprogramming factors (GDF3, DPPA3, DNMT3B, GAL), which could only be detected in 2102EP in vivo or reprogrammed TCam-2 cells." (PMID 31130628, 2019). "Thus, in contrast to the murine system, SOX17 presumably is not involved in the differentiation of human seminomas into a cell type resembling a mixed non-seminoma." (PMID 27283990, 2016). "We stratified the TCGA dataset of 156 samples into a seminoma expression signature (SOX17, PRAME, PRDM1 positive; SOX2, DNMT3B, GAL negative) and an EC expression signature (SOX2, DNMT3B, GAL positive; SOX17, PRAME, PRDM1 negative)." (PMID 32418994, 2020). "In TCam-2-ΔSOX2 cells, the switch from SOX17 to SOX2 is not possible and prolonged expression of SOX17/OCT3/4 contributes to maintenance of a seminoma fate." (PMID 27283990, 2016).
seminoma (continued). "Although the vast majority of cells stained positive for the seminoma markers SOX17, OCT3/4 and TFAP2C, small areas displayed absence of staining of these pluripotency- and seminoma-related genes, pointing at a heterogeneity of the tumor tissues (red arrows)." (PMID 27283990, 2016). "We postulate that the small subpopulation of OCT3/4/SOX17/TFAP2C negative cells is highly similar to in vitro differentiated TCam-2 and thus resembles a mixed non-seminoma in vivo." (PMID 27283990, 2016). "Similar to seminomas, non-seminomas express OCT3/4 and NANOG, with the addition of SOX17." (PMID 38791003, 2024). "Furthermore, TCam-2-ΔSOX2/FOXA2 derived tumors stained positive for pluripotency and seminoma markers OCT3/4, SOX17, TFAP2C, and PRDM1/BLIMP1, but were negative for the differentiation-markers AFP and EOMES." (PMID 31130628, 2019).
gastric cancer (17 papers, 2012 to 2025). A primary or metastatic malignant neoplasm involving the stomach. "Studies focusing on gastric cancer patients showed that methylation of ctDNA in SOX17 and APC were independently associated with poor survival." (PMID 30087854, 2018). "For gastric cancer methylated SOX17 and APC were independent predictors of survival, with an adjusted HR of 3.0 (95% CI 1.2–7.8) and 4.6 (95% CI 1.1–20.3) respectively." (PMID 30087854, 2018). "Hypermethylation of SOX17 promoter was correlated with poor prognosis in esophageal and hepatocellular carcinoma, as well as in colorectal and gastric cancer among other cancers." (PMID 27355345, 2016). "Real time quantitative PCR showed that SOX17 expression was lower in gastric cancer tissues than those in normal tissues." (PMID 22928040, 2012). "SOX17 methylation was detected in both early and advanced gastric cancer, regardless of differentiation type, so it could be a useful biomarker in gastric cancer diagnosis." (PMID 31752198, 2019). "Fukamachi found that CD133(+) cells specifically expressed Sox17, of which overexpression inhibits the growth of gastric cancer, suggesting that Sox17 may be a key transcription factor controlling CD133 expression." (PMID 26503471, 2015). "SOX17 and an epigenetic pathway involving circular RNA ITCH and miR-199-5p were shown to regulate αKlotho expression in gastric cancer cells." (PMID 37958253, 2023). "Another study also investigating the detection of methylated DNA in gastric juice-derived exosomes found that patients with GC had reduced LINE1 methylation whereas SOX17 gene methylation was detected in both early and advanced gastric cancer of both intestinal and diffuse type." (PMID 36428707, 2022). "Ye noted that by downregulating SOX17 expression, the expression levels of cyclin D1 and P27 were upregulated, thereby shortening the cell cycle and promoting the proliferation and invasion of MKN45 gastric cancer cells." (PMID 36072972, 2022).